RNF139 (ring finger protein 139)
Description:
E3-ubiquitin ligase; acts as a negative regulator of cell proliferation through mechanisms involving G2/M arrest and cell death. Required for MHC class I ubiquitination in cells expressing the cytomegalovirus protein US2 before dislocation from the endoplasmic reticulum (ER). Affects SREBP processing by hindering the SREBP-SCAP complex translocation from the ER to the Golgi, thereby reducing SREBF2 target gene expression. Involved in the sterol-accelerated degradation of HMGCR. This is achieved through binding of RNF139 to INSIG1 and/or INSIG2 at the ER membrane. In addition, interaction of RNF139 with AUP1 facilitates interaction of RNF139 with ubiquitin-conjugating enzyme UBE2G2 and ubiquitin ligase AMFR, leading to ubiquitination of HMGCR. The ubiquitinated HMGCR is then released from the ER into the cytosol for subsequent destruction. Required for INSIG1 ubiquitination. May be required for EIF3 complex ubiquitination.
Synonyms: TRC8; RCA1; HRCA1
Tractability: Antibody: UniProt predicts a signal peptide or a membrane-spanning region. PROTAC: UniProt records ubiquitination sites on it; ubiquitination databases record sites on it.
Gene: Protein-coding gene on chromosome 8 (124,474,866 to 124,488,618, forward strand). Ensembl gene ENSG00000170881.
Subcellular location: Endoplasmic reticulum membrane
Pathways (Reactome):
Metabolism of proteins: ER Quality Control Compartment (ERQC)
Gene Ontology:
Molecular function: protease binding; protein binding; ubiquitin protein ligase activity; ubiquitin-like protein transferase activity; ubiquitin-protein transferase activity; signaling receptor activity; zinc ion binding
Biological process: ERAD pathway; negative regulation of cell population proliferation; negative regulation of translation; positive regulation of ubiquitin-dependent protein catabolic process; protein destabilization; protein ubiquitination; regulation of ER to Golgi vesicle-mediated transport; regulation of protein processing; endoplasmic reticulum mannose trimming; proteasome-mediated ubiquitin-dependent protein catabolic process
Cellular component: Derlin-1 retrotranslocation complex; endoplasmic reticulum; endoplasmic reticulum membrane; membrane; endoplasmic reticulum quality control compartment
Genetic constraint (gnomAD): Loss-of-function variants: 18 observed, 54.13 expected, observed/expected ratio (o/e) 0.33, 90% interval 0.23 to 0.49. The upper end of that interval is the gene's LOEUF score, 0.49, which puts it in group 2 of 6, group 1 being the genes least tolerant of losing a copy. Missense variants: 619 observed, 848.88 expected, observed/expected ratio (o/e) 0.73, 90% interval 0.68 to 0.78. Synonymous variants: 325 observed, 318.12 expected, observed/expected ratio (o/e) 1.02, 90% interval 0.93 to 1.12.
Homologues: Orthologues: chimpanzee RNF139 (99% identical), macaque RNF139 (98% identical), pig RNF139 (95% identical), rat Ndufb9 (94% identical), mouse Rnf139 (94% identical), rabbit RNF139 (94% identical), dog RNF139 (90% identical), guinea pig RNF139 (89% identical), tropical clawed frog rnf139 (70% identical), zebrafish rnf139 (68% identical), Drosophila melanogaster Trc8 (36% identical). Paralogues in human: RNF145 (24% identical), SYVN1 (12% identical), AMFR (11% identical), DZIP3 (9% identical).
Diseases named in the same sentence as RNF139 in open-access papers:
RNF139 is named in the same sentence as 18 diseases in open-access papers, as found by Europe PMC text mining. Sharing a sentence is not in itself a finding about the gene and the disease. The quoted sentences say what the papers report.
renal carcinoma (7 papers, 2011 to 2022). A carcinoma arising from the epithelium of the renal parenchyma or the renal pelvis. "Translocation in renal carcinoma, chromosome 8 gene (TRC8)/RNF139 was identified as a tumor suppressor gene product associated with renal carcinoma." (PMID 24957874, 2011). "In addition to SAIH2, E3 ligase RNF139 interacts with HMOX1 and mediates its ubiquitination and degradation, which contributes to the tumor-suppressive effect of RNF139 in renal carcinoma cells." (PMID 36147464, 2022). "Interestingly, RNF139 has been previously regarded as a tumor-suppressive factor in several cancers, including tongue cancer, renal cancer, kidney carcinoma A498 cells, osteosarcoma U2OS cells, and cervical carcinoma HeLa cells." (PMID 34106407, 2021).
glioma (4 papers, 2021 to 2024). A benign or malignant brain and spinal cord tumor that arises from glial cells (astrocytes, oligodendrocytes, ependymal cells). "Recent findings indicate that both lncRNA ARST and E3 Ubiquitin Ligase RNF139 possess inhibitory effects on glioma progression." (PMID 38189823, 2024). "Altogether, we demonstrate the aberration in RNF139 expression in glioma tissue samples and cell lines." (PMID 34106407, 2021). "Secondly, RNF139 overexpression and knockdown was achieved in glioma cell lines and the specific effects of RNF139 overexpression or knockdown on cancer cell proliferation, apoptosis, migration, and invasion were investigated." (PMID 34106407, 2021). "RNF139 serves as a tumor-suppressor in glioma by inhibiting glioma cell proliferation, migration, and invasion and promoting glioma cell apoptosis through regulating PI3K/AKT signaling." (PMID 34106407, 2021). "In the present study, we firstly confirmed the abnormal downregulation of RNF139 in glioma tissues and cell lines." (PMID 34106407, 2021). "By contrast, when RNF139 was knocked down in glioma cell lines, cell viability, DNA synthesis, and cell migration and invasion were all enhanced, whereas cell apoptosis was inhibited." (PMID 34106407, 2021). "Altogether, in the current study, for the first time, we tried to reveal the biological functions and the potential molecular mechanism of RNF139 in glioma." (PMID 34106407, 2021). "Herein, we firstly confirmed the abnormal downregulation of RNF139 in glioma tissues and cell lines." (PMID 34106407, 2021). "In cell lines, the expression of RNF139 was dramatically downregulated in glioma cell lines, including U87, SHG-44, GOS-3, and TJ905 compared with that in human astrocyte cell lines, SVG P12 and HA." (PMID 34106407, 2021). "In the present study, we firstly found the abnormal downregulation of RNF139, an E3 ubiquitin ligase, in glioma tissue samples and cell lines." (PMID 34106407, 2021). "In a word, we demonstrate the aberration in RNF139 expression in glioma tissue samples and cell lines." (PMID 34106407, 2021). "RNF139 serves as a tumor-suppressor in glioma by inhibiting cancer cell proliferation, migration, and invasion and promoting cancer cell apoptosis through regulating PI3K/AKT signaling." (PMID 34106407, 2021). "In both glioma cell lines, RNF139 overexpression significantly inhibited tumor cell viability, DNA synthesis, and cell migration and invasion, whereas promoted cell apoptosis." (PMID 34106407, 2021). "We observed that the tumor-suppressive role of RNF139 in glioma cells through regulating the possible downstream signaling (PI3K/AKT signaling)." (PMID 34106407, 2021). "Consistent with its abnormal downregulation in glioma, ectopic RNF139 expression significantly suppressed glioma cell proliferation, migration and invasion, and promoted cell apoptosis; RNF139 knockdown exerted opposite effects on glioma cell phenotypes." (PMID 34106407, 2021). "Moreover, in two glioma cell lines, RNF139 overexpression inhibited, whereas RNF139 knockdown enhanced the phosphorylation of phosphatidylinositol 3-kinase (PI3K) and AKT serine/threonine kinase 1 (AKT)." (PMID 34106407, 2021). "Considering the tumor-suppressive role of RNF139 in several cancers, we hypothesize that RNF139 also plays a tumor-suppressive role against glioma." (PMID 34106407, 2021). "The downregulation of RNF139 in glioma suggests that RNF139 might play a role in glioma development." (PMID 34106407, 2021). "Thus, to investigate the specific role of RNF139 in glioma carcinogenesis, we conducted ectopic expression or knockdown of RNF139 in glioma cells and examined the cell viability, DNA synthesis, cell apoptosis, migration, and invasion." (PMID 34106407, 2021). "Similarly, the protein levels of RNF139 were significantly decreased in glioma cell lines, including U87, SHG-44, GOS-3, and TJ905 compared with those in human astrocyte cell lines, SVG P12 and HA." (PMID 34106407, 2021).
glioma (continued). "The abnormal downregulation of RNF139 suggests that it may serve as a tumor-suppressor against glioma." (PMID 34106407, 2021). "Moreover, in two glioma cell lines, for the first time, RNF139 was identified that played a tumor suppressor role through regulating PI3K/AKT signaling." (PMID 34106407, 2021). "In glioma cells, ectopic RNF139 overexpression could inhibit, whereas RNF139 knockdown could aggravate the aggressive behaviors of glioma cells, including hyperproliferation, migration, and invasion." (PMID 34106407, 2021). "Our basic experimental outcomes provided sufficient results to uncover a newfound mRNA/signaling pathway regulatory network of RNF139/PI3K/AKT signaling in glioma, supplying a crucial perception concerning the regulatory theory in glioma advancement and new therapeutic options of glioma diseases." (PMID 34106407, 2021). "Thus, RNF139 overexpression could inhibit the hyper-activation of the PI3K/AKT signaling pathway in glioma cells." (PMID 34106407, 2021). "Therefore, we investigated whether the PI3K/AKT signaling pathway could also be affected by RNF139 in glioma cells." (PMID 34106407, 2021). "For instance, TRIM26 is overexpressed in glioma and suppresses ferroptosis via the degradation of GPX4, while RNF139 inhibits glioma cell growth through PI3K/AKT signaling in a ubiquitination-dependent manner." (PMID 39075053, 2024). "In both glioma cell lines, RNF139 overexpression dramatically decreased the ratio of p-PI3K/PI3K and p-AKT/AKT; on the contrary, RNF139 knockdown induced by either shRNA1-RNF139 or shRNA2-RNF139 elevated the ratio of p-PI3K/PI3K and p-AKT/AKT." (PMID 34106407, 2021).
breast carcinoma (3 papers, 2018 to 2022). "RNF139 is a driver gene closely associated with breast cancer." (PMID 36077333, 2022).
tongue cancer (3 papers, 2017 to 2023). A malignant neoplasm affecting the tongue. "A study reported that RNF139 was significantly downregulated in tongue cancer tissue and experimentally that silencing RNF139 enhanced the viability and aggressiveness of tongue cancer cells." (PMID 38106991, 2023). "In tongue cancer cells, RNF139 silencing dramatically enhanced cancer cell invasion and enhanced SCC25 cell tumorigenicity in nude mice." (PMID 34106407, 2021). "The immunoblotting was recruited to determine the expression level of RNF139 in human tongue cancer tissues and para-carcinoma tissues." (PMID 28662643, 2017). "We demonstrated that RNF139 was a suppressor of tongue cancer SCC9 and SCC25 cells growth and invasion." (PMID 28662643, 2017). "In order to find the oral cancer related E3 ubiquitin ligases, we screened the human E3 ubiquitin ligase library and found that RING finger protein 139 (RNF139) regulated the biological behavior of tongue cancer cells." (PMID 28662643, 2017). "In order to find the oral cancer related E3 ubiquitin ligases, we screened the human E3 ubiquitin ligase library and found that RING finger protein 139 (RNF139) regulated the proliferation of tongue cancer cells." (PMID 28662643, 2017). "After determining the correlation between RNF139 and tongue cancer, we further analyze the regulating mechanism of RNF139 on tongue cancer." (PMID 28662643, 2017). "The effect of RNF139 on tumorigenicity of tongue cancer cells was analyzed by xenograft model on immunodeficient Balb/c nude mice." (PMID 28662643, 2017). "Taken together, these data suggest that RNF139 inhibits cell viability and invasion of tongue cancer SCC9 and SCC25 cells." (PMID 28662643, 2017). "To analyze the role of RNF139 in human lung cancers, we detected the protein level of RNF139 in 23 tongue cancer patients’ tumor tissues through western blotting." (PMID 28662643, 2017). "In this study, we further analyzed the role of RNF139 on the development of tongue cancer." (PMID 28662643, 2017). "Our data clearly establish a correlation between RNF139 and tongue cancer." (PMID 28662643, 2017). "Our data establish a role for RNF139 in regulating the progression of tongue cancer." (PMID 28662643, 2017). "While human tongue cancer tissues had low expression of RNF139." (PMID 28662643, 2017). "Furthermore, we determined the low expression of RNF139 in human tongue cancer tissues." (PMID 28662643, 2017). "In order to elaborate the role of RNF139 in regulating the biological behavior of tongue cancer, we analyzed the viability changes of tongue cancer cells, SCC9 and SCC25 cells, induced by RNF139." (PMID 28662643, 2017).
colorectal cancer (1 paper, 2025). A primary or metastatic malignant neoplasm that affects the colon or rectum. "The downregulation of the ubiquitin ligase RNF139 in multidrug-resistant colorectal cancer leads to the upregulation of HMGCR, thereby enhancing cholesterol synthesis." (PMID 39944823, 2025).
tumor (12 papers, 2009 to 2025). "RNF139, also known as TRC8, encodes a multi-membrane spanning protein resides in ER, and it has been revealed to act as a tumour suppressor." (PMID 38106991, 2023). "In these cancer cells, ectopic RNF139 expression has been reported to induce cell cycle arrest, suppress cancer cell proliferation, migration and invasion, and inhibit the tumor formation in nude mice." (PMID 34106407, 2021). "Ring finger protein 139 (RNF139) is a membrane-bound E3 ubiquitin ligase serving as a tumor suppressor by ubiquitylation-dependently suppressing cell growth." (PMID 34106407, 2021). "Knockdown of RNF139 markedly promoted the volumes of the tumor xenografts." (PMID 28662643, 2017). "Hence, the roles of RNF139 in cancer may depend upon the tumour types, and cell-based and animal experiments are warranted to determine the specific roles of RNF139 in PC." (PMID 38106991, 2023). "Moreover, in a RING-dependent manner, RNF139 suppressed the tumor formation in a nude mouse model." (PMID 34106407, 2021). "Dysregulation of this balance, such as reduced RNF139 activity, results in HMGCR overexpression, contributing to drug resistance and tumor progression." (PMID 40370434, 2025). "RNF139 (also known as TRC8) is a membrane-bound E3 ubiquitin ligase, which plays a tumor-suppressive role by ubiquitylation-dependently suppressing cell growth." (PMID 34106407, 2021). "Consistently, the protein levels of RNF139 were significantly decreased in tumor tissues compared with those in adjacent non-cancerous tissues (N = 5)." (PMID 34106407, 2021). "Ubiquitination (via SCF-FBXW7, RNF20, RNF139) or deacetylation (via SIRT1) promotes SREBP1 degradation, inhibiting fatty acid metabolism and maintaining lipid homeostasis. mTORC1 activation and SREBP1 acetylation enhance its stability and promote lipid metabolism, supporting tumor growth." (PMID 40370434, 2025).
cancer (10 papers, 2015 to 2023). A tumor composed of atypical neoplastic, often pleomorphic cells that invade other tissues. "RNF139 ubiquitinated and degraded the antioxidant enzyme heme oxygenase-1 (HO-1) and suppressed HO-1-induced cancer cell growth, migration and invasion." (PMID 28662643, 2017). "Seven genes (BORA, DIS3, POLR2C, FAM175A, EME1, RNF139 and SHMT1) are considered potential biomarkers and/or potential targets for radiotherapy and chemotherapy, as well as cancer susceptibility, cancer progression and metastasis-related genes." (PMID 26517092, 2015). "GOLIM4 and RNF139 in this PM were found as potential cancer drivers in various types of cancers." (PMID 26317392, 2015).
RNF139 also shares sentences with these, for which no sentence is quoted: infection (2 papers); cervical carcinoma (1); dysgerminoma (1); HCMV infection (1); hemangioblastoma (1); lung carcinoma (1); oral cancer (1); osteosarcoma (1); renal cell carcinoma (1); thyroid cancer (1); viral infection (1).